RASGEF1B (RasGEF domain family member 1B)
Description:
Guanine nucleotide exchange factor (GEF) with specificity for RAP2A, it doesn't seems to activate other Ras family proteins (in vitro).
Synonyms: GPIG4; FLJ31695
Tractability: Antibody: its Gene Ontology location is reachable by antibodies, with medium confidence.
Gene: Protein-coding gene on chromosome 4 (81,426,393 to 82,044,244, reverse strand). Ensembl gene ENSG00000138670.
Subcellular location: Early endosome; Late endosome; Midbody
Subcellular location (Human Protein Atlas): Nucleoplasm; Vesicles
Gene Ontology:
Molecular function: guanyl-nucleotide exchange factor activity
Biological process: Ras protein signal transduction; small GTPase-mediated signal transduction
Cellular component: plasma membrane; early endosome; late endosome; midbody
Genetic constraint (gnomAD): Loss-of-function variants: 20 observed, 45.35 expected, observed/expected ratio (o/e) 0.44, 90% interval 0.31 to 0.64. The upper end of that interval is the gene's LOEUF score, 0.64, which puts it in group 2 of 6, group 1 being the genes least tolerant of losing a copy. Missense variants: 377 observed, 448.48 expected, observed/expected ratio (o/e) 0.84, 90% interval 0.77 to 0.92. Synonymous variants: 132 observed, 159.61 expected, observed/expected ratio (o/e) 0.83, 90% interval 0.72 to 0.96.
Homologues: Orthologues: chimpanzee RASGEF1B (100% identical), macaque RASGEF1B (99% identical), dog RASGEF1B (98% identical), guinea pig Rasgef1b (98% identical), rabbit RASGEF1B (98% identical), mouse Rasgef1b (97% identical), pig RASGEF1B (95% identical), rat Rasgef1b (95% identical), tropical clawed frog rasgef1b (87% identical), zebrafish rasgef1ba (86% identical), zebrafish rasgef1bb (70% identical), Drosophila melanogaster CG7369 (51% identical), and 2 more. Paralogues in human: RASGEF1C (68% identical), RASGEF1A (60% identical), RAPGEF2 (25% identical), RAPGEF4 (23% identical), RAPGEF6 (23% identical), RAPGEF3 (23% identical), RASGRF1 (23% identical), RALGDS (23% identical), RAPGEF1 (22% identical), RAPGEF5 (22% identical), RASGRF2 (22% identical), RGL1 (21% identical), and 12 more.
Diseases named in the same sentence as RASGEF1B in open-access papers:
RASGEF1B is named in the same sentence as 13 diseases in open-access papers, as found by Europe PMC text mining. Sharing a sentence is not in itself a finding about the gene and the disease. The quoted sentences say what the papers report.
Intellectual disability (3 papers, 2015 to 2023). "It should be taken into account that chromosome 4 has been weakly associated with mood disorders, and some genes on chromosome 4, such as RASGEF1B, MAPK10 and JNK3, are associated with intellectual disability." (PMID 26539248, 2015). "The PRKG2 (cGMP-dependent protein kinase) and RASGEF1B (RasGEF domain family member 1B) genes have been identified as positional candidate genes for growth restriction, aggression, self-injurious behaviours, and mental retardation in affected German Shepherd dogs." (PMID 37048405, 2023).
hepatocellular carcinoma (1 paper, 2025). A malignant tumor that arises from hepatocytes. "In hepatocellular carcinoma, aberrant expression of circular RNA DHPR promotes tumor growth and metastasis by regulating the RASGEF1B/RAS/MAPK axis." (PMID 40873572, 2025).
liver cancer (1 paper, 2024). An epithelial or non-epithelial malignant neoplasm that arises from the liver. "In mechanism, circDHPR was found to inhibit liver cancer tumorigenesis and progression by regulating the RASGEF1B/RAS/MAPK signaling pathway." (PMID 39616161, 2024).
liver steatosis (1 paper, 2025). "Steatosis severity was associated with upregulation of COL5A3 and TP53I3, whereas upregulated RASGEF1B, S100A12, and TGFBR3 were linked to early-stage liver steatosis." (PMID 40689242, 2025).
Sepsis (1 paper, 2016). Sepsis is defined as life-threatening organ dysfunction caused by a dysregulated host response to infection. "Although our understanding of this new molecular member in sepsis remains sparse, experimental knockdown of a circRNA, RasGEF1B, deciphers the complex interaction of multiple cellular pathways in sepsis." (PMID 27890015, 2016).
tumor (3 papers, 2020 to 2025). "In GSE45436, SNHG11, CRNDE, MYLK‐AS1, E2F3, and CHEK1 were highly expressed in the tumor group, while RASGEF1B was the opposite, which were consistent with the results of TCGA." (PMID 33232580, 2020). "However, mRNA RASGEF1B was downregulated in the tumor group, which deserves further investigation." (PMID 33232580, 2020).
cancer (1 paper, 2024). A tumor composed of atypical neoplastic, often pleomorphic cells that invade other tissues. "Furthermore, its close homolog, RASGEF1B, has been reported to play a functional role in macrophages and chemotaxis, which hinted at the possibility that RASGEF1 proteins assume multifaceted roles in both cancer-related signaling and immune modulation." (PMID 39335143, 2024).
psychiatric disease (1 paper, 2025). "Our results also showed that many psychiatric disease-associated remarkable genes, were upregulated (SLC35F1, SNHG5, and FAM118A) or downregulated (SLC26A3, SLC27A4, LINGO1, and RASGEF1B) in PBMCs of patients with WD." (PMID 40384935, 2025).
RASGEF1B also shares sentences with these, for which no sentence is quoted: developmental delay (1 paper); infection (1); mood disorder (1); neurologic disorders (1); steatosis (1).